IGKV1D-43 (immunoglobulin kappa variable 1D-43)
Description:
V region of the variable domain of immunoglobulin light chains that participates in the antigen recognition. Immunoglobulins, also known as antibodies, are membrane-bound or secreted glycoproteins produced by B lymphocytes. In the recognition phase of humoral immunity, the membrane-bound immunoglobulins serve as receptors which, upon binding of a specific antigen, trigger the clonal expansion and differentiation of B lymphocytes into immunoglobulins-secreting plasma cells. Secreted immunoglobulins mediate the effector phase of humoral immunity, which results in the elimination of bound antigens. The antigen binding site is formed by the variable domain of one heavy chain, together with that of its associated light chain. Thus, each immunoglobulin has two antigen binding sites with remarkable affinity for a particular antigen. The variable domains are assembled by a process called V-(D)-J rearrangement and can then be subjected to somatic hypermutations which, after exposure to antigen and selection, allow affinity maturation for a particular antigen.
Synonyms: IGKV1D43; L23; L23a
Gene: Immunoglobulin variable (V) gene on chromosome 2 (90,209,873 to 90,210,529, forward strand). Ensembl gene ENSG00000242580.
Subcellular location: Secreted; Cell membrane
Gene Ontology:
Biological process: immune response
Cellular component: extracellular region; immunoglobulin complex; plasma membrane
Homologues: Orthologues: chimpanzee IGKV1D-43 (91% identical), mouse Igkv15-103 (69% identical). Paralogues in human: IGKV1-39 (88% identical), IGKV1D-39 (88% identical), IGKV1-12 (87% identical), IGKV1D-13 (87% identical), IGKV1D-16 (87% identical), IGKV1-8 (86% identical), IGKV1D-12 (86% identical), IGKV1-16 (85% identical), IGKV1-6 (85% identical), IGKV1-9 (85% identical), IGKV1D-8 (85% identical), IGKV1-17 (84% identical), and 81 more.